RN7SL19P (RNA, 7SL, cytoplasmic 19, pseudogene)
Gene: Miscellaneous RNA gene on chromosome 8 (70,654,578 to 70,654,883, reverse strand). Ensembl gene ENSG00000243532.
Homologues: Orthologues: chimpanzee Metazoa_SRP (100% identical), macaque Metazoa_SRP (89% identical). Paralogues in human: RN7SL1 (80% identical), RN7SL2 (79% identical), RN7SL3 (79% identical), RN7SL45P (78% identical), RN7SL15P (77% identical), RN7SL296P (77% identical), RN7SL172P (76% identical), RN7SL230P (76% identical), RN7SL302P (76% identical), RN7SL444P (76% identical), RN7SL575P (76% identical), RN7SL664P (76% identical), and 700 more.